ENSG00000287020 (novel transcript)
Gene: Long non-coding RNA gene on chromosome 15 (46,317,393 to 46,351,753, forward strand). Ensembl gene ENSG00000287020.
Gene Ontology:
Biological process: RNA processing
Cellular component: nucleolus